FCN1 (ficolin 1)
Diseases named in the same sentence as FCN1 in open-access papers (continued):
Sharing a sentence is not in itself a finding about the gene and the disease.
acute myeloid leukaemia (4 papers, 2019 to 2024). "Specifically, we concentrate on investigating FCN1’s clinical prognostic relevance, distinct immunological features, potential functional mechanisms, and drug targeting predictions in acute myeloid leukemia (AML)." (PMID 39139822, 2024). "Our investigation primarily focused on the clinical prognostic attributes, immune profiles, potential molecular mechanisms, and candidate therapeutic agents concerning FCN1 and acute myeloid leukemia (AML)." (PMID 39139822, 2024). "The ROC analysis suggests high potential of ficolin-1 to differentiate between acute myeloid leukaemia patients and healthy subjects." (PMID 32601370, 2020). "Our recent investigations revealed markedly lower ficolin-1 concentrations in patients suffering from multiple myeloma or acute myeloid leukaemia (before chemotherapy), compared with controls." (PMID 32635486, 2020).
colorectal cancer (4 papers, 2016 to 2025). A primary or metastatic malignant neoplasm that affects the colon or rectum. "In colorectal cancer, tumor-enriched FCN1+ monocyte-like cells exhibited a high resemblance to blood CD14+ monocytes, likely representing a monocyte population that migrates into tumors and adopts a tumor-specific transcriptional program." (PMID 40367012, 2025). "Despite the existence of multiple well-characterized colorectal-cancer-associated macrophage subgroups, including C1QC+ TAMs, SPP1+ TAMs, and FCN1+ TAMs, we identified a kind of tumor-resident FOLR2+ LYVE1+ macrophage subgroup in colorectal cancer." (PMID 36172359, 2022). "A similar behavior in a different contest has been reported in patients undergoing colorectal cancer surgery who display an early reduction of ficolin-1, followed by a rebound at longer time points (up to 2 weeks) with no relation to CRP changes." (PMID 26792363, 2016).
idiopathic pulmonary fibrosis (4 papers, 2022 to 2025). Idiopathic pulmonary fibrosis (IPF) is a nonneoplastic pulmonary disease that is characterized by the formation of scar tissue within the lungs in the absence of any known cause. "A recent study suggests that expression of Fcn1, Spp1, and Fabp4 is enhanced in monocyte-derived, pro-fibrotic, and normal alveolar macrophage populations of idiopathic pulmonary fibrosis." (PMID 35892659, 2022). "FCN1, FABP4, and SPP1 macrophages are involved in the pathogenesis of lung fibrosis; SPP1 macrophages demonstrate upregulated expression in both SSc-ILD and IPF." (PMID 38937794, 2024).
type 1 diabetes (4 papers, 2014 to 2023). "Likewise, polymorphisms in the ficolin-1(FCN1) coding gene have been associated with an early onset of type 1 diabetes mellitus in a Brazilian population." (PMID 36569030, 2022). "Researchers have shown that UNC13B, PFKFB3, FCN1 and SLC11A1 were diagnostic markers for type 1 diabetes." (PMID 36837510, 2023). "The trans-eSNPs showing mediation by GATA2 (3q21.3), FCN1 (9q34.3), and RPS26 (12q13.2) are also associated with white blood cell subtypes, systemic inflammation (and FCN1 protein activity), and type 1 diabetes risk, respectively." (PMID 25474530, 2014). "GSEA analysis also revealed that patients with obstructive CAD with higher expression levels of NCF2, MYO1F, S1PR4, and FCN1 in PBMC showed enriched pathways in viral myocarditis, Leishmania infection, type I diabetes mellitus, and hematopoietic cell lineage." (PMID 31245869, 2019).
asthma (3 papers, 2021 to 2025). "We conducted further analysis to assess the diagnostic value of ficolin-1 in asthma using the receiver operating characteristic (ROC) curve." (PMID 37996869, 2023). "The ROC curve of plasma ficolin-1 revealed a satisfactory diagnostic capacity in asthma." (PMID 37996869, 2023). "Collectively, ficolin-1 could be employed as a potential diagnostic marker and therapeutic target for asthma." (PMID 37996869, 2023). "Asthma patients with higher plasma ficolin-1 levels demonstrated poorer lung function than those with lower plasma ficolin-1 levels." (PMID 37996869, 2023). "Our data indicated a negative correlation between elevated ficolin-1 expression and pulmonary function, with asthma patients exhibiting worse lung function when their plasma ficolin-1 levels were high." (PMID 37996869, 2023). "Patients with asthma exhibited significantly elevated plasma ficolin-1 levels (median, 493.9 ng/mL; IQR, 330.2–717.8 ng/mL) in comparison to healthy controls (median, 330.6 ng/mL; IQR, 233.8–371.1 ng/mL)." (PMID 37996869, 2023). "The results revealed that asthmatic patients had higher plasma ficolin-1 concentrations, which decreased after ICS treatment and were linked to their lung function, implying a potential involvement of ficolin-1 in asthma pathogenesis." (PMID 37996869, 2023). "Our research demonstrated the elevation of plasma ficolin-1 in asthma patients and correlations between its expression and lung function and ACQ score, thereby providing the first evidence of the effect of ficolin-1 on asthma." (PMID 37996869, 2023). "We classified asthma patients according to their plasma ficolin-1 levels, using the lower limit of the upper quartile for healthy control subjects (371.1 ng/mL) as a cut-point." (PMID 37996869, 2023). "Plasma ficolin-1 concentrations in the asthma group (median, 493.9 ng/mL; IQR, 330.2–717.8 ng/mL) were significantly higher than those of the healthy control group (median, 330.6 ng/mL; IQR, 233.8–371.1 ng/mL)." (PMID 37996869, 2023). "Further, the associations of plasma ficolin-1 level with pulmonary function and asthma control questionnaire (ACQ) score were examined in the asthma patients." (PMID 37996869, 2023). "Our data was the initial evidence of ficolin-1 expression in asthma patients, with asthmatic patients displaying significantly higher plasma ficolin-1 levels than healthy controls." (PMID 37996869, 2023). "Additionally, asthma patients with high ficolin-1 levels had worse lung function than those with low plasma ficolin-1 levels." (PMID 37996869, 2023). "Fourth, our study was a 4-week observational study, which was not sufficient to determine asthma severity, and therefore the association between asthma severity and ficolin-1 expression was not evaluated." (PMID 37996869, 2023). "Additionally, the correlation of ficolin-1 expressions with pulmonary function and clinical syndromes in asthma patients was also analyzed." (PMID 37996869, 2023). "Taken together, these results suggest that elevated ficolin-1 may play a role in asthma development." (PMID 37996869, 2023). "First, though we found that asthma patients have higher levels of ficolin-1 in their plasma, we did not investigate the expression of ficolins in bronchoalveolar lavage fluid or induced sputum." (PMID 37996869, 2023).
atherosclerosis (3 papers, 2022 to 2024). A disease characterized by the build-up of fatty material and calcium deposition in the arterial wall resulting in partial or complete occlusion of the arterial lumen. "We identify a key macrophage subgroup (C2 FCN1+ macrophages) associated with atherosclerosis, which interacts with endothelial cells via CCL, CXCL, APP, and other pathways to regulate disease progression." (PMID 39726810, 2024). "A series of single-cell sequencing analysis methods were used to infer the cell trajectory and identify the key macrophage subsets C2 FCN1+ macrophages associated with atherosclerosis, and interact with endothelial cells through CCL, CXCL, APP, and other pathways." (PMID 39726810, 2024). "In conclusion, we identified the key macrophage subpopulation C2 FCN1+ macrophages associated with atherosclerosis by using a series of methods of single-cell analysis and interacted with endothelial cells through CCL, CXCL, APP, and other pathways to regulate the progression of atherosclerosis." (PMID 39726810, 2024). "It was suggested that C0 C1QC+ macrophages, C1 SPP1+ macrophages, and C2 FCN1+ macrophages may play an important role in the progression of atherosclerosis." (PMID 39726810, 2024). "The results of gene set enrichment analysis, Monocle2, and Slingshot suggest that C2 FCN1+ macrophages may play an important role in the progression of atherosclerosis." (PMID 39726810, 2024). "C2 FCN1+ macrophages interact with endothelial cells via CCL, CXCL, APP, and other pathways to regulate the progression of atherosclerosis." (PMID 39726810, 2024). "Genes such as FCN1, IL1B, and SERPINA3 are involved in immune cell infiltration and regulate atherosclerosis (AS) through ceRNA." (PMID 36686646, 2022). "C0 C1QC+ macrophages, C2 FCN1+ macrophages, and C4 FCER1A+ macrophages had high chromosome copy number variation, which may be related to the progression of atherosclerosis." (PMID 39726810, 2024).
diabetes (3 papers, 2018 to 2022). "HK3, FCN1,CAMK1, GLUT1/SLC2A1 and GLUT3/SLC2A3 are involved in glucose and insulin metabolism that played vital role in development of obesity and diabetes." (PMID 29876008, 2018).
Kawasaki disease (3 papers, 2017 to 2020). A rare inflammatory disease characterized by an acute febrile, systemic, self-limiting, medium-vessel vasculitis primarily affecting children. "Interestingly, part of the benefit of intravenous immunoglobulin (IVIG) therapy relies on ficolin-1 pulldown (reported for Kawasaki disease, the most common form of acquired heart disease in childhood)." (PMID 30619357, 2018). "This study provided support for direct interaction of IVIG with ficolin-1, giving rise to the captivating idea that at least one mechanism of treatment effectiveness of IVIG in Kawasaki disease is due to reduction of ficolin-1 level in the serum." (PMID 33584675, 2020).
lymphoma (3 papers, 2019 to 2020). A malignant (clonal) proliferation of B- lymphocytes or T- lymphocytes which involves the lymph nodes, bone marrow and/or extranodal sites. "Both papers documented possible associations of factors specific for the lectin pathway of complement (especially on genetic background) with multiple myeloma or lymphoma (MBL, ficolin-1, ficolin-2) or hospital infections (MASP-2, ficolin-3)." (PMID 32047495, 2019). "The median of ficolin-1 (as well as of ficolin-2 and−3) for patients diagnosed with lymphomas was not compared with the C or MM groups as their previous medication may affect their serum level." (PMID 32047495, 2019).
vasculitis (3 papers, 2013 to 2021). "FCN1 is also up-regulated in PBMCs from DBA/2 mice suffering from severe vasculitis following injection with Candida albicans water-soluble fraction (CAWS), a putative model mouse of KD16." (PMID 28900133, 2017).
anaemia (2 papers, 2023 to 2025). "It is plausible that increased levels of ficolin-1 with infection are contributing to parasite clearance and even possibly to anaemia via cell lysis." (PMID 40422078, 2025). "As ficolin-1 was negatively associated with Hb concentration, we propose that increased levels of ficolin-1 with infection could contribute to malaria-related anaemia by increasing lysis of uninfected RBCs in addition to iRBCs." (PMID 40422078, 2025). "Binding of ficolin-1 to both the iRBCs and uninfected RBCs may contribute to their lysis, parasite clearance, and potentially anaemia." (PMID 40422078, 2025).
autoimmune conditions (2 papers, 2024 to 2025). "Some other studies suggested the potential immunogenetic relevance of FCN1 polymorphisms in other autoimmune conditions." (PMID 41285030, 2025).
bacteremia (2 papers, 2019 to 2020). "Interestingly, we noted significantly higher median serum ficolin-1 level in LYMPH patients who experienced bacteremia (751 ng/ml) compared with those who had no complications during their hospital stay (371 ng/ml, p = 0.00009)." (PMID 32047495, 2019). "Interestingly, significantly higher median serum ficolin-1 level in LYMPH patients who experienced bacteremia compared with those who had no complications during their hospital stay was found." (PMID 32047495, 2019).
inflammatory bowel disease (2 papers, 2023). A spectrum of small and large bowel inflammatory diseases of unknown etiology. "In addition, FCN1 (ficolin-1) from FCN1+ TAMs can be as a novel macrophage infiltration-associated biomarker for the diagnosis of pediatric inflammatory bowel diseases." (PMID 38347955, 2023).
leukemia (2 papers, 2019 to 2024). A malignant (clonal) hematologic disorder, involving hematopoietic stem cells and characterized by the presence of primitive or atypical myeloid or lymphoid cells in the bone marrow and the blood. "Given the aberrant expression and dysregulation of FCN1 in leukemia, our investigation primarily focused on elucidating its association with clinical characteristics and prognosis in AML." (PMID 39139822, 2024). "To further elucidate the relationship between FCN1 and drug sensitivity, we curated multiple datasets on leukemia drug treatments from literature sources." (PMID 39139822, 2024).
malaria (2 papers, 2013 to 2025). Malaria is a serious and sometimes fatal disease caused by a parasite that commonly infects a certain type of mosquito which feeds on humans. "Using samples from a well-described cohort in Malawi, we show for the first time that ficolin-1 is increased with malaria and inflammation and is negatively associated with Hb." (PMID 40422078, 2025). "It is known that ficolin-1 is released along with neutrophil degranulation, which likely occurs in malaria." (PMID 40422078, 2025). "This is the first time that ficolin-1 concentrations have been measured in a cohort of individuals with malaria, and we saw that ficolin-1 was increased in those with disease compared to HCs." (PMID 40422078, 2025). "We measured ficolin-1 and ficolin-2 concentrations in plasma from Malawian children presenting with uncomplicated or severe malaria or healthy controls (HCs) by ELISA." (PMID 40422078, 2025). "It is likely that the increased concentrations of ficolin-1 in children with malaria in this cohort are due to increased numbers of leukocytes in those infected with Plasmodium spp." (PMID 40422078, 2025). "Unlike ficolin-1, we did not see associations between ficolin-2 concentrations and any of the two clinical types of malaria studied." (PMID 40422078, 2025). "In conclusion, the data presented in this paper suggest for the first time that ficolin-1 may have an important role in malaria disease." (PMID 40422078, 2025). "Unlike with ficolin-1, we did not see a clear association between ficolin-2 concentrations and malaria." (PMID 40422078, 2025). "To further understand whether ficolins play any role in the human immune response to malaria, we determined whether ficolin-1 and ficolin-2 concentrations varied with malaria disease and disease severity in plasma samples collected from children residing in a malaria endemic area." (PMID 40422078, 2025).
multiple myeloma (2 papers, 2019 to 2020). "For the first time, we found a possible association of FCN1 polymorphism with multiple myeloma: the genotype G/A-C/C-G/G (at positions −542, −144, and +6658, respectively) was more common among patients than among controls, although the difference only reached borderline significance." (PMID 32047495, 2019). "Median serum of ficolin-1 concentration in patients suffering from multiple myeloma (800 ng/ml; n = 187) was significantly lower than in healthy controls (1,277 ng/ml; n = 255; p < 0.000001), independently of complications recorded during hospital stay or sex (not shown)." (PMID 32047495, 2019).
Obesity (2 papers, 2017 to 2018). Accumulation of substantial excess body fat. "It is noteworthy that multiple C1q homologs, adiponectin, FCN1–2, and C1qTNF7 showed changes in obesity." (PMID 28559893, 2017).
pneumonia (2 papers, 2016 to 2020). An acute, acute and chronic, or chronic inflammation focally or diffusely affecting the lung parenchyma, caused by an infection in one or both of the lungs (by bacteria, viruses, fungi, or mycoplasma.). "In contrast, babies with confirmed infections (mainly pneumonias) had higher ficolin-1 levels compared with newborns with no infections before leaving hospital." (PMID 33193407, 2020).
rheumatic fever (2 papers, 2023 to 2025). A post-bacterial multisystem inflammatory disease occurring as a post-infectious, nonsuppurative sequela of untreated streptococcus pyogenes (Group A streptococcus [GAS]) pharyngitis, and mainly occurs in individuals aged 5 to 15 years. "Prior studies showed that increased levels of Ficolin-1 at the mRNA and protein levels exerted a protective role against rheumatic fever via bacterial elimination." (PMID 38149246, 2023).
systemic inflammatory response syndrome (2 papers, 2020 to 2023). SIRS is a serious condition related to systemic inflammation, organ dysfunction, and organ failure. "Furthermore, heterozygosity for the rare FCN1 gene mutation, rs148649884 (+6658 G>A, Ala218Thr) was reported in one case of neonatal systemic inflammatory response syndrome (SIRS)." (PMID 38193083, 2023).
acute myocardial infarction (1 paper, 2019). Necrosis of the myocardium, as a result of interruption of the blood supply to the area. "FCN1, CD14, S100A9, ALDH2, hsa-let-7d, hsa-let-7b, hsa-miR-124-3, and hsa-miR-9-1 were identified as potential candidate regulators in acute myocardial infarction." (PMID 30886860, 2019).
autoimmune hepatitis (1 paper, 2020). Hepatitis caused by autoantibodies. "Next, we measured ficolin-1 levels in patients with liver diseases other than PBC, such as chronic hepatitis C or autoimmune hepatitis." (PMID 32915797, 2020). "The ficolin-1 levels in the patients with chronic hepatitis C without cirrhosis (204 ng/mL; P < 0.001) or autoimmune hepatitis (302 ng/mL; P = 0.003) were significantly higher than those of the healthy controls." (PMID 32915797, 2020).
Cirrhosis (1 paper, 2020). A chronic disorder of the liver in which liver tissue becomes scarred and is partially replaced by regenerative nodules and fibrotic tissue resulting in loss of liver function. "The results of the present study demonstrate that serum levels of ficolin-1 was associated with the development of cirrhosis-related conditions in patients with PBC." (PMID 32915797, 2020). "Low ficolin-1 levels were significantly associated with the development of cirrhosis-related conditions independent for histological stage and ALP levels (hazard ratio: 0.933; 95% confidence interval: 0.875–0.994; P = 0.032)." (PMID 32915797, 2020). "We measured four different PRMs (mannose-binding lectin [MBL], ficolin-1, ficolin-2 and ficolin-3) using stored sera, and retrospectively analyzed the associations between PRMs and laboratory findings, histological findings, and the development of cirrhosis-related conditions." (PMID 32915797, 2020). "Kaplan-Meyer analysis of the development of cirrhosis-related conditions was performed using 25th percentile of ficolin-1 levels (cut-off value: 77 ng/mL)." (PMID 32915797, 2020). "The Kaplan-Meyer plot showed a higher rate of development of cirrhosis-related conditions in the patients with low ficolin-1 levels than that in those with high ficolin-1 levels (log-rank; P = 0.028)." (PMID 32915797, 2020). "The ficolin-1 levels in the patients with hepatitis C-related cirrhosis were higher than those of the healthy controls, although the difference was not statistically significant (139 ng/mL; P = 0.41)." (PMID 32915797, 2020). "Patients with low levels of ficolin-1 (< 77 ng/mL) had a significantly increased rate of developing cirrhosis-related conditions." (PMID 32915797, 2020). "The association between ficolin-1 and the development of cirrhosis-related conditions was independent of histological stage and ALP, which are predictors of prognosis in patients with PBC." (PMID 32915797, 2020). "The multivariate analyses showed that ficolin-1 levels were significantly associated with the development of cirrhosis-related conditions independent of histological stage and ALP levels (Hazard ratio, 0.933; 95% confidence interval, 0.875–0.994, P = 0.032)." (PMID 32915797, 2020).